RNU7-164P (RNA, U7 small nuclear 164 pseudogene)
Gene: Small nuclear RNA gene on chromosome X (40,535,502 to 40,535,563, reverse strand). Ensembl gene ENSG00000238730.
Homologues: Orthologues: macaque U7 (89% identical), pig U7 (79% identical). Paralogues in human: RNU7-52P (84% identical), RNU7-11P (82% identical), RNU7-13P (82% identical), RNU7-2P (82% identical), RNU7-3P (82% identical), RNU7-41P (82% identical), RNU7-7P (82% identical), RNU7-160P (81% identical), RNU7-25P (81% identical), RNU7-26P (81% identical), RNU7-35P (81% identical), RNU7-56P (81% identical), and 142 more.